DFFA (DNA fragmentation factor subunit alpha)
Description:
Inhibitor of the caspase-activated DNase (DFF40).
Synonyms: DFF-45; ICAD; DFF1; DFF45
Tractability: Antibody: its Gene Ontology location is reachable by antibodies, with high confidence. PROTAC: ubiquitination databases record sites on it; its protein half-life has been measured.
Gene: Protein-coding gene on chromosome 1 (10,456,522 to 10,472,549, reverse strand). Ensembl gene ENSG00000160049.
Subcellular location: Cytoplasm
Subcellular location (Human Protein Atlas): Cytosol; Plasma membrane
Pathways (Reactome):
Programmed Cell Death: Apoptosis induced DNA fragmentation
Gene Ontology:
Molecular function: deoxyribonuclease inhibitor activity; protein binding
Biological process: negative regulation of apoptotic DNA fragmentation; negative regulation of execution phase of apoptosis; apoptotic process; apoptotic DNA fragmentation; regulation of apoptotic process
Cellular component: chromatin; cytosol; nucleus; protein-containing complex; nucleoplasm; cytoplasm
Genetic constraint (gnomAD): Loss-of-function variants: 16 observed, 31 expected, observed/expected ratio (o/e) 0.52, 90% interval 0.35 to 0.78. The upper end of that interval is the gene's LOEUF score, 0.78, which puts it in group 3 of 6, group 1 being the genes least tolerant of losing a copy. Missense variants: 395 observed, 428.52 expected, observed/expected ratio (o/e) 0.92, 90% interval 0.85 to 1. Synonymous variants: 158 observed, 180.2 expected, observed/expected ratio (o/e) 0.88, 90% interval 0.77 to 1.
Homologues: Orthologues: chimpanzee DFFA (97% identical), macaque DFFA (94% identical), rat Dffa (78% identical), pig DFFA (77% identical), guinea pig DFFA (77% identical), mouse Dffa (76% identical), dog DFFA (69% identical), tropical clawed frog dffa (41% identical), zebrafish dffa (38% identical), Drosophila melanogaster Drep1 (21% identical), Drosophila melanogaster Drep3 (12% identical). Paralogues in human: CIDEB (16% identical), CIDEA (15% identical), CIDEC (15% identical).
Diseases named in the same sentence as DFFA in open-access papers:
DFFA is named in the same sentence as 44 diseases in open-access papers, as found by Europe PMC text mining. Sharing a sentence is not in itself a finding about the gene and the disease. The quoted sentences say what the papers report.
colon cancer (5 papers, 2010 to 2018). "Moreover, miR-196a2 targets DFFA (DNA fragmentation factor subunit alpha) responsible for apoptosis and downregulated in esophageal carcinoma and colon cancer." (PMID 29705927, 2018).
breast carcinoma (4 papers, 2018 to 2022). "Moreover, a genome-wide association study (GWAS) of breast cancer declared identification of 65 novel loci associated remarkably with a high risk of breast cancer at P < 5 × 10− 8 such as FES, MAP 3 K11, CLK2, GRK7, USP25, DFFA, PKP1, and ZKSCAN3." (PMID 35650591, 2022). "As a counterexample, ADAR1, which is much less expressed in breast cancer, targets the 3′ UTR of DNA fragmentation factor subunit alpha (DFFA) transcript, therefore promoting cancer cell invasion." (PMID 35898396, 2022).
neuroblastoma (3 papers, 2002 to 2013). Neuroblastoma (NB) is the most common solid, extracranial childhood tumor. "We hope that this conclusion will prompt others to study these genes, in particular DFFA, in their neuroblastoma tumour material." (PMID 11870543, 2002). "Forty-four neuroblastoma primary tumours were analyzed by sequence analysis for mutations in the coding region of the CASP9 and DFFA genes, and in the promoter region of DFFA." (PMID 11870543, 2002). "Both the CASP9 (OMIM number 602234) and the DFFA (OMIM number 601882) genes have recently been localized to 1p36.2, a region commonly deleted in neuroblastoma tumours." (PMID 11870543, 2002). "In the present study we have examined two other genes in neuroblastoma primary tumours, CASP9 and DFFA." (PMID 11870543, 2002).
asthma (1 paper, 2022). "One of these genes, DFFA, has been implicated with asthma risk through GWASs and colocalization in EURs." (PMID 36341024, 2022).
leukemia (1 paper, 2019). A malignant (clonal) hematologic disorder, involving hematopoietic stem cells and characterized by the presence of primitive or atypical myeloid or lymphoid cells in the bone marrow and the blood. "Each validated gene in this category, i.e., CD3G, DFFA, GIGYF1, GIGYF2, and INTS3 were shown to play a role in neoplastic processes, including leukemia." (PMID 31709175, 2019).
osteoporosis (1 paper, 2019). A condition of reduced bone mass, with decreased cortical thickness and a decrease in the number and size of the trabeculae of cancellous bone (but normal chemical composition), resulting in increased fracture incidence. "In the osteoporosis group, VEGFA, DFFA, and FAM193A genes showed a significant association." (PMID 31747953, 2019). "Excluding genes without known specific functions (CDC27 and TNRC18), ARID2, HEBP1, LTBP1, and PLVAP were the only significant differences in the cancer group revealed by the gene-score methodology, while DFFA, FAM193A, and VEGFA were the only significant differences in the osteoporosis group." (PMID 31747953, 2019).
schizophrenia (1 paper, 2023). A major psychotic disorder characterized by abnormalities in the perception or expression of reality. "Previous studies have shown that genes such as PMAIP1, DNAJC3, DFFA, and BTG3 are involved in apoptosis, but their specific mechanism of action in schizophrenia needs to be further explored." (PMID 37383091, 2023).
tumor (10 papers, 2002 to 2025). "Upregulation of the anti-apoptotic genes BCL2L2, BAG3, and downregulation of pro-apoptotic genes DAXX, FAF1, PAK1, DFFA, ENDOG was found in reprogrammed tumours pointing to a cell cycle arrest without engagement of the apoptotic pathway." (PMID 29662623, 2018). "The analyzed fragments of the genes UBE4B, KIF1B, PGD, DFFA and PEX14 were not methylated in the panel of NB primary tumours and cell lines." (PMID 15740626, 2005). "The genes UBE4B, KIF1B, PGD, APITD1, DFFA and PEX14 are down-regulated in high stage NB tumours, a feature that can not be explained by CpG island methylation." (PMID 15740626, 2005). "Hence, the six genes UBE4B, KIF1B, PGD, APITD1, DFFA and PEX14 are down-regulated in high stage NB tumours, a feature that can not be explained by methylation, rather by a mechanism still remaining to be discovered." (PMID 15740626, 2005).
infection (7 papers, 2013 to 2025). The state of being infected such as from the introduction of a foreign agent such as serum, vaccine, antigenic substance or organism. "Interestingly, another gene near SNP2253, DNA fragmentation factor subunit alpha (DFFA; 35 kb upstream of SNP2253), plays an important role in the cellular machinery orchestrating apoptosis in response to infection." (PMID 31311473, 2019).
DFFA also shares sentences with these, for which no sentence is quoted: cancer (13 papers); mastitis (11); Bovine mastitis (2); conjunctivitis (2); endometrial carcinoma (2); hospital-acquired infections (2); keratitis (2); ovarian serous carcinoma (2); renal cell carcinoma (2); acne (1); adenoma (1); bacteremia (1); bacterial infections (1); bladder cancer (1); blood stream infections (1); Cirrhosis (1); dermatosparaxis (1); diabetic foot ulcers (1); endophthalmitis (1); esophageal carcinoma (1); esophageal squamous cell carcinoma (1); infectious disease (1); kidney cancer (1); leiomyoma (1); liver diseases (1); nasal polyps (1); neurodegenerative disease (1); neuromuscular disease (1); ocular infections (1); osteomyelitis (1).
A further 5 diseases each share a sentence with DFFA in 1 paper.